SST (somatostatin)
Diseases named in the same sentence as SST in open-access papers (continued):
Sharing a sentence is not in itself a finding about the gene and the disease.
Obesity (25 papers, 2010 to 2025). Accumulation of substantial excess body fat. "The underlying molecular mechanisms of SST mediated anti-obesity role and its five receptor subtypes are not well understood." (PMID 32272767, 2020). "Since obesity alters the expression of these systems in different tissues and is associated to MG (patho) physiology, we sought to investigate the role of SST/CORT in regulating GH/IGF-I system in the MGs of lean and obese mice." (PMID 25806796, 2015). "In addition, we highlight recent progress and contribution of SST and its receptors in food-seeking behaviour, obesity (orexigenic), and satiety (anorexigenic) associated pathways and mechanism." (PMID 32272767, 2020). "Therefore, the main focus of this section is the role of GCs in the regulation of food intake and obesity, and we further discuss the role of SST in association with GCs in appetite." (PMID 32272767, 2020). "In conclusion, our study sheds light on the significant role of maternal somatostatin expression during fetal development in influencing the metabolic outcomes of adult offspring, particularly in the context of diet-induced obesity." (PMID 40066865, 2025). "Other GPCRs involved in neurohormonal signalling and associated with obesity and insulin resistance, such as OPRK1 and ADRB2, and receptors for peptide hormones, including somatostatin (SSTR1/2/5) and secretin (SCTR), were also enriched in K cells." (PMID 39441374, 2025). "In the human brain, the obesity cluster was significantly enriched for regions of open chromatin in cell types including intratelencephalic (IT) projecting neurons, somatostatin-positive (SST+) GABAergic inhibitory neurons and D1 medium spiny neurons." (PMID 38374256, 2024). "Presented examples of regulatory role of ASTs clearly indicate their structural and functional homology with vertebrate GAL and SST, hormones which are closely connected with obesity." (PMID 34681728, 2021). "In the search for new models for studying obesity, the homology observed between insect allatostatins, vertebrate somatostatin (SST), and galanin (GAL) is of interest." (PMID 34681728, 2021). "Ghrelin levels are known to be decreased in obesity, while the density of somatostatin-producing cells remains unchanged in the gastric mucosa of obese mice, and plasma gastrin levels are increased in HFD mice." (PMID 32824949, 2020). "In conclusion, these findings link delta-cell dysfunction and SST resistance in alpha-cells directly to metabolic disease and demonstrated the importance of SST for the regulation of glucagon secretion in obesity and prediabetes." (PMID 32446876, 2020). "The purpose of the present study was to determine if immunization with somatostatin vaccines in a polygenic, diet-induced-obesity (DIO) mouse model was effective in reducing weight gain and increasing weight loss." (PMID 22958753, 2012). "The use of somatostatin vaccines for treatment of obesity is based upon previous studies using GH therapy and the accepted endocrine model of somatostatin to down-regulate growth hormone releasing hormone (GHRH), GH and IGF-1." (PMID 22958753, 2012). "There are different studies that suggest that the pathophysiological mechanism responsible for the GH hyposecretion of obesity is probably multifactorial; there is a chronic state of somatostatin hypersecretion, increased FFA and decreased ghrelin." (PMID 20150954, 2010). "Estimation of other insulin and glucagon regulators like somatostatin and incretins could have also been included to give us a wholesome picture of insulin and glucagon secretion in obesity and in different glucose tolerance states." (PMID 38665134, 2024). "In addition, about 36% of CCKVMH co-express somatostatin (Sst), which is important for regulating factors in the satiety system and obesity." (PMID 39529694, 2024).
Obesity (continued). "Another anti-obesity vaccine under development is the anti-somatostatin, which promises to remove the inhibitory effects of somatostatin on growth hormone (GH) and IGF-1 secretion, thus inhibiting the increase in adiposity associated with low levels of these hormones." (PMID 34444990, 2021). "Accordingly, understanding the role of SST and the neurohormonal pathways involved in satiety and obesity may assist with developing novel SST analogues and potential treatment strategies." (PMID 32272767, 2020). "The expression of SST in hypothalamic regions including ARC, VMN, and LHA and D cells of GIT demonstrating its role in food-seeking behaviour and in the regulation of hormonal secretion as well as gut motility are compelling pieces of evidence to support the role of SST in satiety and obesity." (PMID 32272767, 2020). "Our results also suggest that SST, and possibly CORT, might play a pivotal role in the pathological association between obesity-associated changes and MG tumorigenesis." (PMID 26956474, 2016). "In addition, octreotide can improve the low level of somatostatin in obesity, improve insulin resistance and pancreatic fat, and inhibit the intestinal absorption of fat." (PMID 27002331, 2016). "Brain transcriptome analyses in obese mice identified several obesity-related pathways (e.g. leptin, somatostatin, and nemo-like kinase signaling), as well as genes involved in feeding and appetite (e.g. Pmch, Neurotensin) and in metabolism (e.g. Bmp4, Bmp7, Ptger1, Cox7a1)." (PMID 25629159, 2015). "Therefore, the increased somatostatin production may be the key connection between gastric acid secretion and obesity but more animal and human studies are needed to verify this hypothesis." (PMID 27207783, 2016). "In contrast, under obesity conditions, CORT-KO and SST-KO had a similar percentage of mammary tumors, although latency in tumor development was lower in CORT-KO than in SST-KO mice." (PMID 26956474, 2016). "To analyze the effect of diet-induced obesity and the implication of SST and CORT in the regulation of GH/IGF-I, SST/CORT and ghrelin systems expression in the MFPs, we used CORT- and SST-KO female mice and their respective control fed a LF or HF diet." (PMID 25806796, 2015). "With this well-established role of BDNF, it can be argued that the absence of BDNF lessen SST effect in obesity independent of inhibitory action of SST in the regulation of key hormones involved in obesity." (PMID 32272767, 2020). "The relationship between SST and obesity does not appear to be simple, and recent evidence points to a divergent action of SST in the brain and in the periphery (gut, stomach, pancreas)." (PMID 30053852, 2018). "We analyzed the interaction of diet-induced obesity with the lack of SST and CORT on the production and secretion of key pituitary hormones by determining GH, IGF and PRL levels at sacrifice." (PMID 27901064, 2016). "In this context, current evidence suggests that SST and its analogues, through binding to different SSTR subtypes on the pancreatic β-cells, decrease the release of insulin, which may be beneficial in the treatment of obesity." (PMID 32272767, 2020). "In contrast to SST-KO mice, lack of endogenous CORT seems to be more important under LF-feeding conditions than in diet-induced obesity conditions." (PMID 27901064, 2016). "In addition to SST analogues, SST vaccinations, namely JH17 and JH18, using intraperitoneal route of administration have been reported in reduction of weight gain and body weight percentage of normal, non-obese mice and mice with diet-induced obesity." (PMID 32272767, 2020).
Hypoglycemia (24 papers, 2012 to 2025). A decreased concentration of glucose in the blood. "Further studies are required to assess functional interactions between islet cell populations following RYGB and possible involvement of loss of somatostatin-induced inhibitory tone from delta-cells in insulin-induced hypoglycemia." (PMID 36137097, 2022). "Exogenous insulin administration promotes somatostatin secretion, which aggravates hypoglycemia by reducing cAMP formation; while somatostatin receptor antagonists improve hypoglycemia by increased cAMP, and associated reduction in oxidative stress." (PMID 32774668, 2020). "Moreover, we observed that SST cells deficiency led to increased insulin content and excessive insulin release, which might contribute to the observed hypoglycemia." (PMID 29880854, 2018). "We demonstrated that SST cell ablation directly induced proportional changes in several types of hormone-producing endocrine cells within the islets and caused excessive insulin synthesis and release, which might contributed to the hypoglycemia." (PMID 29880854, 2018). "Conventional medical therapies for glycemic control demonstrate limited efficacy in NICTH: intravenous glucose provides only transient relief, and glucocorticoids, glucagon, GH, or somatostatin analogs often fail to suppress IGF-2-mediated hypoglycemia." (PMID 41367853, 2025). "Instead, the endogenous secretion of insulin and glucagon was inhibited with somatostatin immediately prior to hypoglycemia and both hormones were matched between groups using intraportal infusions." (PMID 37166980, 2023). "During hypoglycemia, a decrease in somatostatin secretion from the delta cells occurs and this decrement is amplified by factors released from the alpha and beta cells." (PMID 35819935, 2022). "The consistency that both somatostatin and insulin releases are stimulated linearly in a dose-dependent fashion by glucose is instrumental in preventing insulin-induced hypoglycemia." (PMID 33494193, 2021). "The paracrine explanation for diminished responsiveness to hypoglycemia is later found to be excessive somatostatin secretion." (PMID 33494193, 2021). "Repeated 2DG increased SST+ terminals on GHRH neurons, but SST+ terminals on GHRH neurons were unchanged with repeated insulin hypoglycemia." (PMID 33148883, 2020). "The GLP-1 induced increased secretion of glucagon and glucose infusion rates during hypoglycemia despite somatostatin indicate a possible alleviation of hypoglycemia by GLP-1." (PMID 24400077, 2014). "We found an increased secretion of glucagon during hypoglycemia despite somatostatin infusion with GLP-1 infusion and furthermore glucose infusion rates increased in the hypoglycemia study with GLP-1." (PMID 24400077, 2014). "It has been suggested that increased paracrine-mediated alpha-cell inhibition by excessive basal somatostatin secretion from the delta-cells in response to low glucose may be responsible for the aberrant glucagon response to hypoglycemia in T1D." (PMID 38612880, 2024). "The inability to secrete glucagon normally when exposed to hypoglycemia in T1D may be because of intra-islet dysregulation in the absence of insulin secretion from pancreatic ß-cells and/or elevated somatostatin (SST) signalling from nearby pancreatic δ-cells." (PMID 38510652, 2024). "SSTR2a’s have also been shown to restore alpha-cell counterregulatory glucagon secretion in rodents subjected to antecedent hypoglycemia, suggesting that paracrine delta-cell somatostatin feedback inhibition on the alpha-cells increases with each recent bout of hypoglycaemia." (PMID 38612880, 2024). "It was questioned whether somatostatin plays a role during hypoglycemia because somatostatin-secreting δ-cells are downstream of glucagon-secreting α-cells in the islet microcirculation of non-diabetic rats." (PMID 22969729, 2012).
Hypoglycemia (continued). "Some researchers are considering the impact of somatostatin antagonists or agents that suppress somatostatin secretion that could be used along with insulin therapy to restore a more appropriate release of glucagon during hypoglycemia and postprandial or fasting conditions." (PMID 36992764, 2022). "While the intra islet insulin hypothesis might be an important component of iatrogenic hypoglycemia other regulatory mechanism within the islets exist including somatostatin from the delta cells inhibiting both glucagon and insulin secretion in a paracrine fashion." (PMID 34405569, 2021). "Compared to β-cell factors, a conceptual advantage of somatostatin-mediated glucose inhibition of glucagon release is that it may operate also in hypoglycaemia, since glucose stimulates somatostatin release from mouse and human islets at similar concentrations that inhibit glucagon secretion." (PMID 27044660, 2016). "Secretion of GH depends on GHRH, somatostatin (GH-inhibiting hormone, GHIH), and ghrelin, but several other factors are undoubtedly involved in the regulation of GH secretion (e.g., thyroid hormones, hypoglycemia)." (PMID 41155234, 2025). "Unlike dextrose infusions, octreotide, like somatostatin, directly suppresses the pancreatic production of insulin, preventing rebound hypoglycemia." (PMID 39347364, 2024). "Additionally, it has been suggested that excessive delta cell somatostatin secretion in the intra islet milieu augments suppression of alpha cells leading to absent glucagon responses during hypoglycemia." (PMID 34405569, 2021). "According to our original hypothesis, GLP-1 should not be able to inhibit glucagon secretion during hypoglycaemia because no somatostatin would be present under these conditions." (PMID 28551699, 2017). "One could speculate that in normal rats, the high doses of antagonist even have some agonist properties, and confirmed that in normal rats, somatostatin is not a major inhibitor of hypoglycemia-induced glucagon release." (PMID 22969729, 2012).
somatostatinoma (22 papers, 2010 to 2025). A rare, usually malignant neuroendocrine tumor arizing from delta cells. "When suspected due to presence of somatostatinoma triad, a fasting plasma somatostatin level of more than 30 pg/ml is diagnostic." (PMID 31210994, 2019). "Regarding histologic NET subtypes, 58 (62%) cases were SOM-NETs, characterized by extensive somatostatin expression and tubulo-acinar structure, only one of which (2%) was associated with a full-blown somatostatinoma syndrome, 8 (9%) were GPs/CoGNETs, and 27 (29%) were conventional NETs." (PMID 35553369, 2022). "Furthermore, increased levels of SST are not only associated with somatostatinoma of the pancreas but also with various extra-Pancreatic NENs." (PMID 32537434, 2020). "Aberrant elevations of SST are evident in conditions such as somatostatinoma and inflammatory bowel diseases." (PMID 38426092, 2024). "Elevated somatostatin levels in the blood reflect the secretory activity of the tumor, and the ability to detect and quantify circulating somatostatin levels offers a good tool for the diagnosis and management of somatostatinomas." (PMID 38928704, 2024). "As expected, SST expression was significantly higher in the endocrine somatostatinoma cell line QGP1 compared to the three PDAC cell lines AspC1, MiaPaCa2, and T3M4." (PMID 32243066, 2020). "Co‐secretion of insulin (in addition to somatostatin) by the hepatic somatostatinoma was well characterized as mechanism of hypoglycaemia in this patient." (PMID 31592116, 2019). "Consistent with its origin from a human somatostatinoma, expression of SST was elevated in QGP-1 cells in comparison to CORT, but this was not the case for BON-1 cells." (PMID 26673010, 2016). "Following the first two case reports of somatostatin-secreting tumors in 1977, fewer than 200 cases of somatostatinoma have been reported." (PMID 23618063, 2013). "For duodenal somatostatinomas, the somatostatin syndrome can occur only if the tumor is larger than 4cm." (PMID 23618063, 2013). "Since the first two case reports of somatostatin-secreting tumors in 1977, fewer than 200 cases of somatostatinoma have been reported." (PMID 23618063, 2013). "In somatostatinomas symptoms are due to somatostatin hypersecretion (hyperglycaemia, cholelithiasis, diarrhoea and steatorrhoea, hypochlorhydria) or to the mass effect." (PMID 20196864, 2010). "Similarly, somatostatinoma and carcinoid tumors can be excluded through plasma somatostatin and 5-hydroxyindoleacetic acid levels, respectively." (PMID 40291307, 2025). "Interestingly, the very rare somatostatinomas secrete somatostatin (SST), which is a growth-hormone inhibitory peptide with antiproliferative properties." (PMID 40134804, 2025). "However, the presence of somatostatin-producing cells in various tissues and the hormone’s role in normal physiological processes can affect the specificity of circulating somatostatin as a sole marker for somatostatinomas." (PMID 38928704, 2024). "Similarly, somatostatin can be measured to aid in the diagnosis of somatostatinoma and VIP can be measured in the plasma to diagnose a VIPoma in conjunction with hypokalemia and achlorhydria." (PMID 36291833, 2022). "Somatostatinomas (hypersecretion of somatostatin) may present in the pancreas or the duodenum but are rare even in the adult population." (PMID 36291833, 2022). "To check whether HIF2α binds to the promoter region of SST, we performed ChIP-qPCR with an HIF2α antibody in the human pancreatic islet cell carcinoma (somatostatinoma) cell line QGP-1." (PMID 31091718, 2019). "Hence, SST level per se is not sufficient to diagnose somatostatinoma but it requires very careful clinical assessment." (PMID 32537434, 2020).